KLHL33 (kelch like family member 33)
Tractability: Small molecule: it belongs to a druggable protein family.
Gene: Protein-coding gene on chromosome 14 (20,425,852 to 20,436,166, reverse strand). Ensembl gene ENSG00000185271.
Genetic constraint (gnomAD): Loss-of-function variants: 43 observed, 52.93 expected, observed/expected ratio (o/e) 0.81, 90% interval 0.63 to 1.05. The upper end of that interval is the gene's LOEUF score, 1.05, which puts it in group 4 of 6, group 1 being the genes least tolerant of losing a copy. Missense variants: 1,005 observed, 918.61 expected, observed/expected ratio (o/e) 1.09, 90% interval 1.04 to 1.15. Synonymous variants: 416 observed, 398.11 expected, observed/expected ratio (o/e) 1.04, 90% interval 0.96 to 1.13.
Homologues: Orthologues: chimpanzee KLHL33 (99% identical), macaque KLHL33 (96% identical), pig KLHL33 (86% identical), rabbit KLHL33 (84% identical), mouse Klhl33 (79% identical), rat Klhl33 (79% identical), guinea pig KLHL33 (58% identical). Paralogues in human: KLHL20 (20% identical), KLHL1 (19% identical), KLHL17 (19% identical), KLHL4 (19% identical), KEAP1 (19% identical), KLHL5 (19% identical), KLHL32 (18% identical), IPP (18% identical), KLHL13 (18% identical), KLHL8 (18% identical), KLHL9 (18% identical), KLHL34 (17% identical), and 42 more.
Diseases named in the same sentence as KLHL33 in open-access papers:
KLHL33 is named in the same sentence as 5 diseases in open-access papers, as found by Europe PMC text mining. Sharing a sentence is not in itself a finding about the gene and the disease. The quoted sentences say what the papers report.
renal cell carcinoma (1 paper, 2020). "Lower expression of KLHL33 was associated with significantly worsened prognosis in renal cell carcinoma (P = 0.0021)." (PMID 33041663, 2020).
Takayasu arteritis (1 paper, 2023). A rare inflammatory large-vessel vasculitis primarily affecting the aorta and its major branches, but also other large vessels, causing stenosis, occlusion, or aneurysm. "KLHL31, which is abundant in human and mouse cardiomyocytes, was downregulated in human HCM and KLHL33 has been reported as relevant locus in Takayasu’s arteritis in humans." (PMID 36928240, 2023).
thyroid cancer (1 paper, 2021). "Finally, to find prognostic makers of THCA, we performed survival correlation analysis on all genes in samples of thyroid cancer patients, and finally determined five hub genes based on the log-rank value: CD47, CILP, DERA, KLHL33, PSMB8." (PMID 34376710, 2021).
cancer (1 paper, 2018). A tumor composed of atypical neoplastic, often pleomorphic cells that invade other tissues. "Eight of these had decreased expression in cancer (KLHL3, KLHL4, KLHL13, KLHL14, KLHL29, KLHL30, KLHL32, and KLHL33) while four genes (ENC1, KLHL12, KLHL17, and KLHL35) had patterns of up-regulated gene expression." (PMID 30647843, 2018).
KLHL33 also shares sentences with these, for which no sentence is quoted: leprosy (1 paper).